ATG16L1 (autophagy related 16 like 1)
Diseases named in the same sentence as ATG16L1 in open-access papers (continued):
Sharing a sentence is not in itself a finding about the gene and the disease.
bacterial infection (19 papers, 2008 to 2025). "ATG16L1-deficiency induces enhanced IL-1β secretion in dendritic cells in response to bacterial infection." (PMID 39464882, 2024). "The data presented here show that the role of Atg16L1 in the placenta is more similar to that in those other tissues, with loss of the gene leading to increased susceptibility to bacterial infection." (PMID 28018968, 2016). "Furthermore, NOD2 and NOD1 receptors can recruit ATG16L1 proteins upon bacterial infection to activate autophagy, while the A allele of rs2241880 impairs the activation of autophagy to increase the risk of septic shock in VAP patients." (PMID 32940422, 2020). "We wondered whether higher sensitivity to bacterial infection in Atg16L1-deficient placentas was caused by compromised canonical autophagy or whether it could be rescued by induction of autophagic flux." (PMID 28018968, 2016). "The cellular expression of ATG16L1 facilitates bacterial invasion, however the IBD-associated ATG16L1 T300A variant may be protective against bacterial infection." (PMID 25159710, 2014). "Finally, very recent evidence suggests that NOD1 and NOD2 are essential for recruitment of ATG16L1 during bacterial infection, which is impaired in patients with CD-associated NOD mutants." (PMID 21209938, 2010). "During Shigella infection, two important receptor proteins in the NLR family, NOD1 and NOD2, are recruited to the bacterial infection site, and autophagy protein Atg16L1 is recruited simultaneously, triggering autophagy to help remove the bacteria." (PMID 35273506, 2022). "NLRP3 and ATG5/ATG16L1-mediated autophagy signaling pathway plays an important role in regulating immune response to resist bacterial infections." (PMID 36362066, 2022). "For instance, autophagy can be induced by Autophagy related 16 like 1 (ATG16L1)-Transmembrane protein 59 (TMEM59) interactions in response to bacterial infection." (PMID 35694307, 2022). "Travassos suggests that the sub-classes of the NLRs, NOD1, and NOD2 are essential for anti-bacterial infection by recruiting autophagy protein ATG16L1 to the plasma membrane at the bacterial entry site." (PMID 33013364, 2020). "Together, these findings suggest that ATG16L1 and the autophagy pathway in general contribute to protecting the placenta against bacterial infection." (PMID 28018968, 2016). "We asked if WIPI2 interaction with ATG16L1 was also required for the recruitment of the LC3 to the phagophore during bacterial infection." (PMID 24954904, 2014). "We have previously demonstrated that human ATG16L1 is essential for autophagosome formation in human epithelial cells in the contexts of both serum withdrawal and bacterial infection." (PMID 18852889, 2008). "Moreover, intracellular proteins NOD2 and NOD1 exert critical effects on autophagy induction upon bacterial invasion by recruiting ATG16L1 proteins to the site of bacterial infection on cell membrane." (PMID 32940422, 2020). "Such alteration impairs the unconventional autophagic activity of TMEM59, a transmembrane protein that contains the WD40 domain-binding motif, and disrupts its normal intracellular trafficking and its ability to engage ATG16L1 in response to bacterial infection." (PMID 27273576, 2016). "Hence, this is further confirmation that the roles of ATG16L1 in bacterial infections are tissue dependent." (PMID 28018968, 2016). "None of the SNPs in IRGM, ATG16L1 and TNFRSF1A gene was found to be significantly associated with susceptibility to bacterial infection." (PMID 34407136, 2021). "Moreover, both NOD1 and NOD2 can activate autophagy during bacterial infection by a mechanism which is independent of RIP2 and NF-κB, by recruiting the autophagy protein ATG16L1 to the plasma membrane at the bacterial entry site." (PMID 30791886, 2019).
inflammation (4 papers, 2010 to 2026). Aberrant reaction of the microcirculation characterized by movement of fluid and leukocytes from the blood into extravascular tissues. "However, upon loss of both A20 and ATG16L1, spontaneous barrier disintegration and chronic intestinal inflammation develops." (PMID 31015422, 2019). "Thus, an essential component of the autophagic machinery, Atg16L1, suppresses endotoxin-induced intestinal inflammation." (PMID 20161797, 2010). "Moreover, RNA sequencing and lipidomic profiling of PUFA-exposed IECs indicate that ATG16L1 is required for PTGS2/COX2 expression and prostanoid formation, which likely exert inflammatory actions, and PTGS2/COX2-related lipid mediators are thought to contribute to intestinal inflammation in IBD." (PMID 41382985, 2026).
neurodegenerative disease (4 papers, 2018 to 2024). A disorder of the central nervous system characterized by gradual and progressive loss of neural tissue and neurologic function. "However, mice with WDR-deficient ATG16L1 exhibited symptoms of neurodegenerative disease, which is commonly caused by autophagy blockade." (PMID 38674078, 2024). "Recent studies have confirmed that gigaxonin E3 ligase regulates ATG16L1 ubiquitination, affecting autophagy in neurodegenerative diseases." (PMID 38994020, 2024).
metabolic disorders (3 papers, 2019 to 2025). "To summarize, the findings of the present study demonstrated that dysregulation of the FTO/m6A/ATG16L1 axis impairs autophagy in meniscus cells, thereby promoting bioenergetic metabolic disorders and accelerating meniscus degeneration and OA." (PMID 39804978, 2025).
adenocarcinoma (2 papers, 2023 to 2025). A common cancer characterized by the presence of malignant glandular cells. "A group of 14 Xbp1/Rnaseh2bΔIEC mice and 10 Atg16l1/Xbp1/Rnaseh2bΔIEC mice were histopathologically analyzed, which confirmed that both genotypes largely developed adenocarcinomas." (PMID 41057521, 2025).
GI tumor (1 paper, 2025). "The purpose of our studies was to define the interactions, if any, between aramchol and a multi-kinase inhibitor in GI tumor cells at clinically relevant drug concentrations and to define the responses of isogenic cells homozygous for ATG16L1 T300 or ATG16L1 A300." (PMID 40827882, 2025).
kidney (1 paper, 2016). "Moreover, miR-20a regulates hypoxia-induced autophagy by targeting ATG16L1 in ischemic kidney injury." (PMID 27803889, 2016).
ATG16L1 also shares sentences with these, for which no sentence is quoted: cardiovascular disease (3 papers); acute myeloid leukemia (2); acute myocardial infarction (2); pharyngeal cancer (2); Skin rash (2); vitamin D deficiency (2); acute kidney injury (1); adenoma (1); AIDS (1); Allergy (1); amyotrophic lateral sclerosis (1); Arthritis (1); breast tumors (1); calicivirus infection (1); choriocarcinoma (1); clear cell renal carcinoma (1); colorectal tumors (1); diabetic retinopathy (1); dilated cardiomyopathy (1); endothelial dysfunction (1); familial hypercholesterolemia (1); Fanconi anemia (1); gall-bladder cancer (1); gastrointestinal disease (1); glioma (1); graft versus host disease (1); Granuloma (1); Hepatosplenomegaly (1); herpesvirus infection (1); human papillomavirus infection (1).
A further 31 diseases each share a sentence with ATG16L1 in 1 paper.